BRI3 (brain protein I3)
Description:
Participates in tumor necrosis factor-alpha (TNF)-induced cell death. May be a target of Wnt/beta-catenin signaling in the liver.
Synonyms: I3
Tractability: Antibody: its Gene Ontology location is reachable by antibodies, with high confidence; UniProt predicts a signal peptide or a membrane-spanning region.
Gene: Protein-coding gene on chromosome 7 (98,252,379 to 98,310,441, forward strand). Ensembl gene ENSG00000164713.
Subcellular location: Lysosome membrane; Cytoplasm, perinuclear region (Isoform 1); Cytoplasm (Isoform 2); Nucleus
Pathways (Reactome):
Immune System: Neutrophil degranulation
Gene Ontology:
Molecular function: identical protein binding; protein binding
Cellular component: cytoplasm; nucleus; azurophil granule membrane; plasma membrane; lysosomal membrane; perinuclear region of cytoplasm
Genetic constraint (gnomAD): Loss-of-function variants: 6 observed, 8.9 expected, observed/expected ratio (o/e) 0.67, 90% interval 0.37 to 1.33. That is too few expected variants to judge how well the gene tolerates losing a copy. Missense variants: 134 observed, 134.36 expected, observed/expected ratio (o/e) 1, 90% interval 0.87 to 1.15. Synonymous variants: 91 observed, 58.03 expected, observed/expected ratio (o/e) 1.57, 90% interval 1.32 to 1.85.
Homologues: Orthologues: chimpanzee BRI3 (100% identical), dog BRI3 (95% identical), guinea pig BRI3 (95% identical), pig BRI3 (94% identical), mouse Bri3 (94% identical), rat Bri3 (93% identical), tropical clawed frog bri3 (43% identical), zebrafish bri3 (43% identical), Caenorhabditis elegans F11G11.5 (30% identical), Drosophila melanogaster CG12012 (29% identical).
Diseases named in the same sentence as BRI3 in open-access papers:
BRI3 is named in the same sentence as 19 diseases in open-access papers, as found by Europe PMC text mining. Sharing a sentence is not in itself a finding about the gene and the disease. The quoted sentences say what the papers report.
breast carcinoma (3 papers, 2014 to 2025). "In a summary, nifedipine stimulated the proliferation and migration of breast cancer cells via the axis of miRNA-524-5p-BRI3–Erk pathway independently of its calcium channel-blocking activity." (PMID 25436889, 2014). "Silencing BRI3 reversed the promoting effect of nifedipine on the breast cancer." (PMID 25436889, 2014). "Thus the effects of nifedipine on breast cancer is carried out by miRNA-524-5p-BRI3–Erk signaling pathway." (PMID 25436889, 2014). "We therefore developed a new macrophage-specific SPP1 TAM signature (PLAUR, SLC11A1, BRI3, FBP1, C15orf48) using publicly available scRNA-Seq data from lung, colorectal and breast cancers and validated the signature using multiple independently published scRNA-Seq datasets." (PMID 41415295, 2025). "Silencing of BRI3 expression clearly suppressed the phosphorylation of Erk, and consequently the proliferation and migration of MDA-MB-231 cells, suggesting that the BRI3-Erk signaling pathway is involved in regulation of this nifedipine effect on breast cancers." (PMID 25436889, 2014).
Alzheimer disease (2 papers, 2021 to 2023). A progressive, neurodegenerative disease characterized by loss of function and death of nerve cells in several areas of the brain leading to loss of cognitive function such as memory and language. "To date, most studies on BRI3 have focused on its role in Alzheimer's disease; our study is the first to link BRI3 to the molecular typing of pulmonary fibrosis with pulmonary hypertension, which may provide a new avenue for BRI3 functional research." (PMID 34823498, 2021). "In the brain, BRI3 (locus 11, LDL locus in CPA) has been implicated in neuronal survival following ischemia/reperfusion injury and may be a protective regulator against Alzheimer disease." (PMID 38028628, 2023).
pancreatic neuroendocrine tumor (2 papers, 2019 to 2022). Pancreatic endocrine tumor, also known as pancreatic neuroendocrine tumor (PNET), describes a group of endocrine tumors originating in the pancreas that are usually indolent and benign, but may have the potential to be malignant. "MEG3 was also reported to suppress pancreatic neuroendocrine tumor growth by down regulating miR-183/BRI3 axis." (PMID 31488093, 2019).
cerebral infarction (1 paper, 2023). An ischemic condition of the brain, producing a persistent focal neurological deficit in the area of distribution of the cerebral arteries. "The precise mechanism of the neuroprotective effect of miRNA-323 remains unclear, but it may regulate apoptosis during cerebral infarction by targeting the TGF β1/SMAD3 signaling pathway or by modulating BRI3, which is involved in I/R injury-induced neuronal apoptosis." (PMID 37763638, 2023). "Few studies have shown that miR-323-5p controls apoptosis in cerebral infarction conditions by modulating the transforming growth factor-β1 (TGF-β1)/Smad3 signaling pathway or BRI3, but no studies have been conducted regarding the mechanisms associated with DEX." (PMID 37763638, 2023).
COVID-19 (1 paper, 2024). A disease caused by infection with severe acute respiratory syndrome coronavirus 2. "This work identified specific overexpressed genes related to neutrophils only in severe COVID-19 patients, such as SPI1, SLPI, S100A9, and BRI3, which indicates a specific expression regulation that occurs only in SARS-CoV-2 infection." (PMID 38262689, 2024).
dementia (1 paper, 2012). Loss of intellectual abilities interfering with an individual's social and occupational functions. "Although the functions of the British dementia proteins, BRI2 and BRI3, are unknown, the other proteins have been implicated in signal transduction complexes that regulate the balance of neurite outgrowth vs. retraction." (PMID 22768208, 2012).
hepatocellular carcinoma (1 paper, 2018). A malignant tumor that arises from hepatocytes. "Previous studies showed that BRI3 expression is upregulated at both mRNA and protein levels upon β-catenin activation by various approaches, such as lithium treatment and overexpression of Wnt ligands in Huh7 (hepatocellular carcinoma) cell lines." (PMID 30983867, 2018).
hypogonadism (1 paper, 2025). A disorder characterized by decreased function of the gonads. "In colocalization analyses, we find that several variants associated with testosterone levels and hypogonadism risk are located in or near genes related to liver function (UGT2B17, BRI3, PRMT6, PPIF)." (PMID 40316537, 2025).
tumor (7 papers, 2014 to 2024). "miR-183 abolished the tumor suppressor function of MEG3 and upregulated the tumor-promoting function of the BRI3 gene." (PMID 35163032, 2022). "In addition, Zhang and Feng (2017) confirmed that MEG3 might play a tumor-suppressive role in PC by sponging miR-183 and targeting the brain protein I3 (BRI3)." (PMID 36544907, 2022). "In PNETs, tumor hypermethylation and silencing of long noncoding MEG3, determined activation of miR183/BRI3 axis, and cell proliferation due to c-MET oncogene activation." (PMID 33384663, 2020). "When miR-183 activity was increased, it upregulates BRI3, whose positive relationship correlates with p38/ERK/AKT and Wnt/β-catenin pathways, suggesting a complicated tumor-promoting mechanism which includes interaction among MEG3, miR-183, and BRI3 via p38/ERK/AKT and Wnt/β-catenin signaling." (PMID 38279330, 2024).
psychiatric disease (1 paper, 2022). "This miRNA has not been thoroughly studied in the context of psychiatric disease; the current literature does suggest it has a significant role in promoting neuronal apoptosis in the context of ischemia by targeting BRI3 and SMAD3 mRNA." (PMID 36217923, 2022).
BRI3 also shares sentences with these, for which no sentence is quoted: infection (2 papers); breast tumors (1); cancer (1); endometriosis (1); fungal infection (1); glioma (1); hemangioma (1); pulmonary fibrosis (1); pulmonary hypertension (1).